FN1 (fibronectin 1)
Diseases named in the same sentence as FN1 in open-access papers (continued):
Sharing a sentence is not in itself a finding about the gene and the disease.
tumor (continued). "EMT-related epithelial cells, characterized by the expression of genes such as FN1 and VIM, showed activation of pathways that regulate cell adhesion, wound healing, and cell growth, suggesting their potential role in tumor invasion and metastasis." (PMID 40520021, 2025). "Between ARGs_Low tumour cells and T cells, ITGB1-CD46 and ITGB1-ENG were ligand-receptor pairs with strong regulatory potential, while COL1A2, CCL3, SERPINE1, FN1 and CDKN1A were top genes target to TGFB1." (PMID 40830065, 2025). "In vitro experiments confirmed the regulatory effects of STA on p-STAT3, p-JAK and FN1, indicating that STA can effectively inhibit the expression and function of these genes, thereby exerting anti-tumor effects." (PMID 40772037, 2025). "Simultaneously, FN1 activates PI3K/Akt pathways in endothelial cells, upregulating matrix MMP9 expression and promoting vascular wall remodeling, providing channels for tumor cell invasion and metastasis." (PMID 41450464, 2025). "Other notable NET-related CSM and SP genes include previously discussed IGF-2 and IGFBP3 genes and genes related to the stromal component of the tumor (COL5A3, FN1, and NOTCH3)." (PMID 40522948, 2025). "CST significantly suppressed CCN2, LOXL2, DDIT4, and FN1, key drivers of ECM remodeling and angiogenesis, indicating that CST disrupts the structural and metabolic axes sustaining tumor progression." (PMID 41279995, 2025). "While the enrichment of ECM-related pathways is in line with the known roles of THBS2, FN1, COL1A1, and COL5A1 in extracellular matrix remodelling and tumour progression, the concurrent upregulation of mTOR signalling presents an intriguing finding." (PMID 40860666, 2025). "FN1 directly drives PDAC metastasis via the integrin-PI3K/AKT axis and indirectly promotes a “cold tumor” microenvironment by recruiting immunosuppressive cells." (PMID 40678072, 2025). "In this study, we noticed that the promoter regions of five HGs, such as KRT19, MMP1, COL11A1, SDC1, FN1, and COL5A1 were highly methylated in normal compared to tumor patients." (PMID 38639039, 2024). "For instance, FN1 has been shown to be involved in cancer metastasis, while THBS1 regulates angiogenesis and tumor perfusion." (PMID 39593831, 2024). "In terms of information flow, almost all tumour-related signalling pathways show increased activation compared with that in normal samples, including the VEGF, FN1 and FGF pathways." (PMID 37850657, 2024). "Through cell experiments, we found hat overexpression of FN1 and POSTN in CAFs significantly promoted the wound healing and invasion ability of tumor cells." (PMID 38601538, 2024). "The top 5 overexpressed proteins in tumor compared to NT (ranked according to the log2(FC) T vs CT) included SFRP2, KDM5A, CMTM5, HSPA5 and FN1." (PMID 39681068, 2024). "On the other hand, from methylation analysis, we observed that the promoter region of HGs such as KRT19, MMP1, COL11A1, SDC1, FN1, and COL5A1 is significantly methylated in normal tissue than in tumor tissue." (PMID 38639039, 2024). "Based on our data, CD8 Tex cells in LN-out upregulate of TGF-β1, IFN-γ, and ITG-β1, which subsequently target FN1, EGFR, CTNNB1, and COL1A1 in tumor cells, activating the ERK1 and ERK2 cascade pathways and facilitating tumor progression." (PMID 38519500, 2024). "CTShigh and C1Qhigh TAMs generate immunosuppressive interactions with aDTCs via predominantly secretion of SPP1, FN1, TIMP1, or upregulation of CD74, all of which foster tumor-cell metastasis." (PMID 38460015, 2024). "In turn, CD8 Tex cells in the LN-out highly expressed TGF-β1, IFN-γ, and ITGB1, which target FN1, EGFR, CTNNB1, COL1A1, and CFLAR in tumor cells, activating downstream pathways including ERK1 and ERK2 cascade." (PMID 38519500, 2024).
tumor (continued). "FN1 was also an important gene in CTHRC1+GREM1+ myCAF, which has been shown to promote angiogenesis and metastasis of tumor cells through integrin signaling, leading to the activation of the FAK pathway and also contributing to EMT39." (PMID 39075108, 2024). "The results showed that the expression of IPCEF1, TFF3, GLT8D2, TPO and DIO1 were downregulated in the tumor group and DPP4, LRP4, CDH3, KCNJ2, CLDN1, GABRB2, FN1 were upregulated in the tumor group." (PMID 39513122, 2024). "When stimulated by glycolysis and fibronectin 1 (FN-1), HLA-DR- and CD86-high macrophages exhibit a glycolytic phenotype, impeding the secretion of the anti-tumor agent IL-12 p70 through the PKM2/HIF-1α axis." (PMID 38891772, 2024). "Subsequently, we performed IHC staining analysis of VM-related markers, including VM markers VE-cadherin, Fibronectin 1 (FN1), SERPINE2, tumor microenvironment markers MMP2 and MMP9, epithelial cell marker E-cadherin and mesenchymal cell marker vimentin." (PMID 38164156, 2024). "Notable genes displaying similar expression patterns in AFCs and tumour cells compared with FCs included TFF3 and TG (signature genes of FCs), IGHG4 and SFRP2 (signature genes of FCs) and FN1 and SFTPA1 (signature genes of tumour cells)." (PMID 38426403, 2024). "Transferrin receptor (TFRC) and fibronectin 1 (FN1), significant contributors at three months, contributed to the tumor regulation of viral production and multiple tumor cellular activities in cell line models." (PMID 39262965, 2024). "QRT‐PCR assays confirmed that the epithelial gene Cdh1 was significantly downregulated while the mesenchymal genes, Cdh2, Vim and Fn1, were significantly upregulated in the TMPL tumor organoids compared to the TMP organoids." (PMID 39049720, 2024). "We observed that several pro-tumor signal pathways were primarily present between these cells, including MIF, FN1, TGF-β and COLLAGEN pathways." (PMID 37344903, 2023). "Accordingly, there has been an increased production of extracellular matrix proteins such as fibronectin 1 (FN1), MMP1, and MMP9 in chronic inflammatory and tumor states of the cervix." (PMID 36831674, 2023). "Fibronectin 1 (FN1) is referred as biomarkers for epithelial-mesenchymal transition (EMT) or ECM and facilitates tumor growth and metastasis." (PMID 37656377, 2023). "Estrogen activity can modulate components of the ECM in the tumor microenvironment, upregulating transcripts of COL1A1, and several matricellular proteins such as TNC, FN1, and POSTN." (PMID 37056757, 2023). "Lovastatin is suggested to suppress the expression of FN1 and Rho family small GTP-binding proteins, which are known to contribute to tumor aggressiveness through promoting cellular plasticity." (PMID 37568764, 2023). "In the present study, tumor cells were observed to be reduced in BM and highly expressed MUC1, SCGB2A2, FN1, BGN, and PEG10." (PMID 37470685, 2023). "Tumor size-related proteins were involved in angiogenesis (VCAN, VTN, NRP1), EMT (FN1, CD44, THBS2), and translation (EIF1AX, EIF5), further indicating the biological basis of ccRCC growth." (PMID 37460463, 2023). "On the other hand, the expression of many M2 signature genes—including those for FN1, MARCO, MRC1, MSR1, TGF-β1, and TGM2—decreased with tumor progression." (PMID 37441079, 2023). "On the other hand, the results showed that, for LUSC tumor samples, CDH2, SPP1, and TNC were significantly upregulated and FN1, CYR61, SERPINA1, and IL6 were significantly downregulated compared to their respective controls." (PMID 37887075, 2023). "Among them, CDKN2A (also known as P16 gene), FN1, and ITGA5 were identified as tumor markers which predict poor prognosis." (PMID 38248716, 2023). "The exosomes from A549-COX-2 cells improved tumor growth and invasion, and α-SMA and FN1 expression in mesenchyma in tumor tissues coinjected with NIH-3T3-WT cells." (PMID 37723559, 2023).
tumor (continued). "The main figure of the network of regulator effects showed “migration of cells,” “invasive tumor,” “proliferation of cells,” “advanced malignant cancer,” and “apoptosis” through the suppression of genes such as MMP9 and FN1." (PMID 36996146, 2023). "Gene expression of COL1A1, COL1A2, COL6A3, FN1, and THY1 in CAFs as well as COL4A1 and COL4A2 in Angiogenic_EC had a highly significantly positive correlation with the proportion of malignant tumor cells." (PMID 38002057, 2023). "Exosomes and tumor mRNA from primary OC and LN metastatic patients were analyzed for their quantitative gene expression patterns of MMP9, CXCL8, and FN1." (PMID 37640804, 2023). "After systematic data curation, four upregulated (YWHAB, TXNDC12, MYL6B, SFN) and four downregulated (FN1, PSMB6, PRDX4, PEA15) markers in miRNA-overexpressed tumor secretomes were identified." (PMID 37128318, 2023). "The exosomes derived from A549-COX-2 cells upregulated the expressions of α-SMA, FN1, and FAP-1 in both MRC-5 and NIH-3T3 cells, suggesting that tumor-derived exosomes contribute to COX-2-mediated CAFs activation in LUAD." (PMID 37723559, 2023). "This expression pattern was significantly correlated with both FN1 and CLDN7 RPPA protein levels in READ, indicating that the LCN2–SLC22A17–MMP9 network is involved in the TME regulation of this tumor." (PMID 36211450, 2022). "To demonstrate the physical proximity between tumor cells expressing INHBA and ECM-remodeling CAFs, we co-stained nodular and infiltrative BCCs for INHBA and Activin A-exposure signature genes like FN1 and POSTN using RNA FISH." (PMID 35986012, 2022). "More importantly, knockdown of FN1 also relieved the aggressiveness in HOXD11-overexpressing cells, indicating that FN1 was an essential and indispensable mediator in HOXD11-mediated PSCC tumor progression." (PMID 36151071, 2022). "ITGA2 interacted with COL1A1, COL1A2, COL8A1, FN1, and HSPG2, mediating the tumor cell–fibroblast and tumor cell–endothelial cell connection." (PMID 35719923, 2022). "Our results demonstrated that HOXD11 directly bound to FN1 promoter regions and promoted the expression of FN1, which is a vital component of ECM in shaping the tumor microenvironment to promote metastasis." (PMID 36151071, 2022). "We found that mesenchymal-related markers such as FN1, TGFBI, and COL1A1 were enriched in mixed-lineage tumor cells." (PMID 35962452, 2022). "PPI analysis revealed 22 genes for MECa and 63 for AdCC that were validated by Kaplan–Meier that showed FN1 and SPP1 for MECa, and EGF and ERBB2 for AdCC as more significant candidate genes for each neoplasm." (PMID 36146635, 2022). "In the cell subsets of tumor samples, FN1, CLU, and ANXA1 were high expressed in tumor cells and low expressed in myeloid cell and fibroblast." (PMID 35359404, 2022). "Compared with the normal tissues, FN1, IL10, and MYC were highly expressed, while the expression of CD247 was decreased in tumor bladder tissues." (PMID 36389789, 2022). "We have identified some of the molecular characteristics of the high-motility mesenchymal-like phenotype in our patient-derived cell model, most notably high gene expression levels of FN1, CHI3L1, and SERPINE1 in relation to other tumor-derived reactive glia." (PMID 35803925, 2022). "FN1, SOX4 and ETV5 were further validated in HNSCC patients’ tumor tissues with irradiated failures, which is novel radioresistance biomarkers in HNSCC." (PMID 36212151, 2022). "Overexpression of FN1, SOX4 and ETV5 were found in 43 paired samples between paracancerous tissues and tumor tissues of HNSCC." (PMID 36212151, 2022). "The scRNA-seq data showed that ITGA2 was mainly expressed in tumor cells, while its ligands COL1A1, COL1A2, COL8A1, FN1, and HSPG2 were expressed in fibroblasts and endothelial cells." (PMID 35719923, 2022). "FN1 and CLDN7 have been investigated as TME factors involved in the epithelial to mesenchymal transition (EMT) and metastasis in different tumor types." (PMID 36211450, 2022).
tumor (continued). "This further induces the increased secretion of fibronectin 1 and inhibits the occurrence of tumor EMT and tumor metastasis." (PMID 36611857, 2022). "We also stained tumor sections for the core MI components COMP, FN1, CTSB, and VCAN, which were transcriptionally upregulated in PKN2KO tumors; stains were enhanced in invasive regions and in regions of connective tissue." (PMID 35081338, 2022). "Knockdown of major TFs of the TGF-β pathway, SNAI1/2, and SMAD4, led to decreased FN1 expression, consequent EMT inhibition, and decreased tumor cell motility." (PMID 35216235, 2022). "Macrophages are known to promote tumor cell migration through the secretion of proteins, such as EGF, CHI3L1, IGF1, FN1, TNC and TGFBI." (PMID 36551640, 2022). "HOXD11 was mediated by miR-138-5p and induced FN1 transcription and increased MMP2 and MMP9 expression to degrade ECM and promoted tumor metastasis in vivo and in vitro." (PMID 36151071, 2022). "In the cell subsets of normal samples, FN1 and ANXA1 were high expressed in tumor cells and low expressed in myeloid cell and fibroblast; CLU was low expressed in tumor cells and high expressed in myeloid cell and fibroblast." (PMID 35359404, 2022). "Remarkably, we found a positive correlation between INHBA expression in tumor cells and the surrounding expression of Activin A-exposure genes (FN1 or POSTN) in CAFs, with preferential expression in tumor areas with High infiltrative morphology." (PMID 35986012, 2022). "Low expression of miR-138-5p in tumors leads to overexpression of HOXD11, which induced FN1 transcription and increased MMP2 and MMP9 expression to degrade ECM and promoted tumor metastasis in vivo and in vitro." (PMID 36151071, 2022). "By using an immunofluorescence assay, we detected the colocalization of tumor cell–expressed ITGA2 and fibroblast-expressed FN1, indicating a role of ITGA2 and its ligand in regulating tumor cell–fibroblast interactions." (PMID 35719923, 2022). "The results showed that the expression of EMT-related interstitial proteins (Vimentin, N-cadherin, Snail, and FN1) was significantly decreased in the shCOPB2 group, suggesting that COPB2 knockdown significantly inhibited EMT transformation and tumor invasion." (PMID 35600351, 2022). "Recent studies have demonstrated that FN1 activates matrix metalloproteinase 2 (MMP2) and MMP9 expression to hydrolyze components of the basement membrane and thus can promote tumor invasion and metastasis in various cancers." (PMID 36151071, 2022). "A total of six upregulated genes (FN1, APOA1, CXCL8, MMP1, MMP3, and THBS1) in tumor tissue were identified by the differential analysis of 10 hub genes." (PMID 35719376, 2022). "Our research further demonstrates that FN1 is a potential prognostic biomarker and therapeutic target in THCA from the perspective of DNA methylation and tumor immunology." (PMID 35141255, 2021). "A positive correlation was also found between EMT markers (FN1 and CDH2) and the IGF‐1R expression in OSCC tumours." (PMID 34528373, 2021). "To further verify the results of bioinformatics analysis, we applied qRT-PCR to validate the mRNA levels of HMMR, SPP1, FN1, CCNB1, CXCL8, MAD2L1 and CCNA2 in 10 paired tumor and adjacent normal tissues with qRT-PCR." (PMID 34126961, 2021). "In this study, we comprehensively analyzed the correlation between FN1 expression with the prognosis of patients with THCA, as well as with the presence of tumor-infiltrating immune cells." (PMID 35141255, 2021). "In contrast to tumors, the adjacent non-tumor tissues harbored eight genes with recurrent HBV integration, including FN1, DCC, OAZ2, ANO3, ENOX1, GRIK4, NPAT, and SNCAIP." (PMID 34209079, 2021). "Fibrotic lung-derived fibroblasts produce high level of FN1 and the secreted phosphoprotein 1 (SPP1) that chemoattract tumor cells and inhibit their apoptosis by binding to the common integrin αv receptor, expressed by tumor cells." (PMID 33731188, 2021).
tumor (continued). "To understand the clinical meaning of these results per individual patient, we further assessed the correlation of COL6, FN1, or VTN with treatment response in 8 patient- and tumor site-matched metastatic samples." (PMID 34162871, 2021). "We also established their prognostic value in more tumor types and found that in most tumors (such as HNSC, BLCA, and SKCM), high expression of FN1 and SPP1 in immune cells were related to poor prognosis." (PMID 34804043, 2021). "Immune infiltration analysis showed that the expressions levels of COL3A1, RAC1, FN1, and SDC2 in CD4+T cells were significantly higher than those in tumor cells, especially regulatory T cell infiltration was significantly increased in BM tumors." (PMID 34229299, 2021). "The results showed that the expression of C1QC, FN1, and SPP1 increased significantly in TAMs, which indicated that the tumor microenvironment most likely induced their high expression in macrophages." (PMID 34804043, 2021). "A positive correlation was found between the fibronectin (FN1) and IGF‐1R expression in OSCC tumours (p < 0.0001)." (PMID 34528373, 2021). "Integrative analysis of multiomics data identified EGFR, JUN, MYC, FN1 and SERPINE1 as key modulators of the tumour immune microenvironment and potential targets for combination therapies which was validated in two validation sets." (PMID 33971902, 2021). "The ECM components COL1A1, COL3A1, COL4A1, and fibronectin 1 (FN1), are critical regulators during tumor metastasis, so we examined their expression in the DCN and control cells using qPCR." (PMID 34504839, 2021). "The AUC of FN1 expression was 0.694, higher than that of TNM classification (AUC: 0.556) or that of the tumor stage (AUC: 0.543), with a sensitivity of 62.5% and a specificity of 75.0%." (PMID 34746236, 2021). "Previous studies have indicated that FN1 is involved in NKp46 receptor-mediated interferon-γ (IFN-γ) production by natural killer cells, with respect to the control of tumor architecture and metastasis." (PMID 35141255, 2021). "In vivo administration of tumor-derived exosomes in murine lung increases the expression of genes coding for ECM components, including FN1 and MMP-9, as well as proinflammatory and prometastatic chemokines." (PMID 33731188, 2021). "Using qRT-PCR, we validated that their transcriptions in our GC tumor tissue were upregulated except SPP1 and FN1, which correlated with tumor relapse and predicts poorer prognosis in GC patients." (PMID 34126961, 2021). "Analyses of clinical data from three public databases revealed that higher expression of fibronectin-1 (FN1) correlated with poorer prognosis and higher tumour pathological grade in HNSCC." (PMID 33318468, 2020). "Western blot results showed that FN1(11/12),LTBP1(11/12), PLOD2(11/12), RCN3(10/12), THBS1(11/12) were increased in tumor tissues (Paired-samples t-test, p < 0.05), indicating that the screening results of TMT technology were credible." (PMID 32216815, 2020). "Next, we investigated mRNA expression of genes involved in the epithelial-to-mesenchymal transition (EMT), and increased expression of FN1 and VIM was detected in LK0902 and LK0917 tumor cells co-cultured with CAFs." (PMID 33353547, 2020). "CM from both tumor cell lines induced M2 polarization as shown by the increased expression of CD163, FN1, and IL10 mRNAs, and a dramatically reduced expression of these M2 markers was observed in the ezrin-depleted cells." (PMID 33086476, 2020). "Among these genes, COL1A1, COL1A2, FN1 and COL5A2 were considered as perspective effective targets that play prominent roles in the development and recurrence of the tumor, including STAD." (PMID 33193601, 2020). "Significantly decreased levels of expression of both hsa-circ_0081534 and FN1 were found in the sh-circ_0081534 group, whereas hsa-circ_0081534 depletion subsequently and notably increased miR-508-5p expression in NPC tumor afflicted tissues." (PMID 33082297, 2020).